CCL2 (C-C motif chemokine ligand 2)
Diseases named in the same sentence as CCL2 in open-access papers (continued):
Sharing a sentence is not in itself a finding about the gene and the disease.
psoriasis (continued). "Fibroblasts produced a number of chemokines (CCL13, CCL19, CCL2, CCL8, CXCL1, CXCL12, CXCL2, CXCL3) that linked to receptors expressed by myeloid cells and T cells, suggesting an important role for fibroblasts in recruiting immune cells in psoriasis." (PMID 37308489, 2023). "SFN treatment effectively decreased the mRNA expression of Ccl2 compared to psoriasis-induced mice." (PMID 38007430, 2023). "Unexpectedly, pro-inflammatory genes, including CXCL1, CCL2, and IL-1β, which may lead to severe inflammation in psoriasis patients, were downregulated by miR-193b-3p mimics in the presence or absence of M5 treatment." (PMID 34667159, 2021). "CCL2 is seen in several inflammatory diseases, including psoriasis and atopic contact dermatitis." (PMID 34086734, 2021). "Dysregulated Th17 cells and IL-17 synthesis in the skin, synovial space and endothelium promote synthesis of pro-inflammatory cytokines namely IL-1β, TNF and IL-6 and neutrophil chemoattractants such as IL-8, CCL20 and CCL2 as observed in psoriasis and psoriatic arthritis." (PMID 33737877, 2020). "Since BaP stimulates the production of CCL2, which is upregulated in the lesional skin in atopic dermatitis and psoriasis, we next examined whether PAH inhibits BaP-induced CCL2 expression." (PMID 29643980, 2018). "An elevated level of MCP-1 (CCL2) is observed between psoriasis and MI." (PMID 26966903, 2016). "Similarly, the pathogenesis of psoriasis involves key Th1 and Th17 inducing cytokines like TNFα, IL-1β, IL-2, IL-6, IL-10, IL-12p70, IL-23, CCL2, 3, 4, 5, 20, CXCL1, 8, 9 and 10, many of which are induced by cocktail treated DCs." (PMID 20663192, 2010). "Notably, differential expression analysis identified 1,530 up-regulated and 1,435 down-regulated genes in the PLEVP group compared to the model, with several psoriasis-related inflammatory markers (Il17a, Ccl2, Cxcl2, and Tnf) being significantly down-regulated." (PMID 40248109, 2025). "CCL2 (MCP-1), a chemokine of the C-C subfamily, is significantly elevated in psoriasis and atopic dermatitis, contributing to immune cell recruitment and antiviral defense." (PMID 41264606, 2025). "The study highlights six chemokine genes (CCR7, CCL2, CCL19, CXCL8, CXCL1, and CXCL2) as potential biomarkers in psoriasis, which are significantly involved in immune and inflammatory responses." (PMID 38829444, 2024). "Our study highlighted CCR7, CCL2, CCL19, CXCL8, CXCL1, and CXCL2 as potential inflammatory biomarkers in psoriasis, illuminating their molecular mechanisms." (PMID 38829444, 2024). "In conclusion, our study highlights six chemokine genes (CCR7, CCL2, CCL19, CXCL8, CXCL1, and CXCL2) as potential biomarkers in psoriasis, providing insights into the immune and inflammatory responses as pivotal instances in disease pathogenesis." (PMID 38829444, 2024). "Other than having a role in MHC class I antigen presentation, ERAP1 is involved in the activation of inflammasome pathways and production of cytokines and chemokines involved in psoriasis development (i.e., IL-6, TNF-α, and CCL2)." (PMID 38495872, 2024). "High expression of RANTES, MCP-1 (CCL2) and IL-2R appears in the epidermis of patients with AD and in psoriasis patients." (PMID 35216228, 2022). "Most of these targets exhibited abnormal expression and were designated as the therapeutic targets in psoriasis, such as the cytokines and chemokines (IL-1β, IL-6, TNF, IFN-γ, CXCL8, CCL2)." (PMID 34168554, 2021). "The CCR2 ligand CCL2 is expressed by keratinocytes in psoriatic plaques, suggesting a potential role for CCR2 in psoriasis pathogenesis." (PMID 23472158, 2013). "CCL2 is expressed at high levels in psoriatic plaques by keratinocytes, suggesting a potential role for CCR2 in psoriasis pathogenesis." (PMID 23472158, 2013). "Expression of the CCR2 ligand, CCL2 by basal keratinocytes within psoriatic plaques has been detected, suggesting a role for CCR2 in psoriasis pathogenesis." (PMID 23472158, 2013).
psoriasis (continued). "TWEAK can also induce the production of CCL2, RANTES, CCL17, and CCL20 in keratinocytes, and such effect is enhanced by synergistic signals from IL-13 and IL-17, two crucial factors in the pathogenesis of AD and psoriasis." (PMID 29038621, 2017). "Indeed, LS skin contained significantly more CCL2, CCL5, and CXCL1 compared to NL skin, in both classical psoriasis and the GEN001 patient." (PMID 25369198, 2014). "Moreover, this study found significant upregulation of well-known psoriasis-related genes such as β-defensin 2, CD68, and cytokines IL-8 (CXCL8), SCYA2 (MCP-1/CCL2), and platelet-derived endothelial cell growth factor 1 in psoriatic skin lesions." (PMID 19884985, 2009). "For example, chemokines like MIG/CXCL9, IL-10/CXCL10, IL-8/CXCL8, MCP-1/CCL2 and MIP-3α/CCL20 released from epidermal keratinocytes function as potent chemoattractants for monocytes, neutrophils, Langerhans cells, DCs and T cells, which are key cells in psoriasis." (PMID 29232931, 2017). "Additionally, expression of CCL2 mRNA was significantly induced, and there were mild (but not statistically significant) increases in CXCL1, CXCL10, CCL5, and IL-8 in psoriasis-associated mutant CARD14 transfected HDBECs compared to wild-type HDBECs." (PMID 25369198, 2014). "We confirmed that endogenous TWEAK was required for maximal expression of CCL2, CCL5 and CCL7, and furthermore, we found defective production of CCL17 and CCL20 in mice lacking TWEAK in the AD model and the psoriasis model, respectively." (PMID 28530223, 2017). "Psoriasis-specific cytokines (e.g., IL-12, IL-17A, IL-23) did not promote chemokine expression, but TNF-α – which could indicate both infection and sterile inflammation – was able to induce CCL-2 and CXCL10 expression." (PMID 41264606, 2025).
ischemic stroke (97 papers, 2010 to 2025). A stroke disorder caused by obstruction of blood flow to the brain, due to thrombotic (local blood clot formation) or embolic (due to a blood clot or other material traveling from another site) event. "Together, these results provide an additional mechanism by which loss of Slc4a4 modulates BBB function and astrocytic CCL2 via regulating arginine to citrulline/NO conversion in the context of ischemic stroke." (PMID 38709635, 2024). "After adjusting for multiple comparisons, monocyte chemoattractant protein 1 (MCP1/CCL2) showed a significant association with increased risk of overall ischemic stroke, CES, and LAAS." (PMID 39628323, 2024). "Prior literature demonstrated that genetic predisposition to higher levels of CCL2 is associated with higher risk of ischemic stroke." (PMID 33971895, 2021). "CCL2 expression is also associated with the infarct volume which plays a pivotal role in brain inflammation and infarct volume development after ischemic stroke." (PMID 28828208, 2017). "Prospective observational studies support associations of higher circulating CCL2 levels with ischemic stroke and cardiovascular death, whereas Mendelian randomization analyses from population genetic studies show associations with higher risk of ischemic stroke and coronary artery disease." (PMID 40119478, 2025). "In our photothromobotic ischemic stroke model, the upregulation of Cxcl10 and Ccl2 was particularly pronounced in the old mice." (PMID 40867143, 2025). "Following an ischemic stroke episode, dBET1 administration to mice significantly reduces the expression level of CCL2, which in turn attenuates ischemia-induced microglia and astrocyte-reactive gliosis and improves prognosis." (PMID 39206161, 2024). "We further measured cortical CCL2 levels, which were upregulated more than 2-fold in Slc4a4-icKO mice under normal and ischemic stroke conditions compared to WT." (PMID 38709635, 2024). "Monocyte Chemoattractant Protein-1 (MCP-1/CCL2) is one of the most studied chemokines in the pathophysiology of ischemic stroke." (PMID 38178909, 2023). "The CCL2/CCR2 axis mediates monocyte migration in ischemic stroke and affects the integrity of the BBB." (PMID 37452512, 2023). "We found that serum CCL2 levels were significantly increased in ischemic stroke patients compared to healthy controls (U = 185, p = 0.0001)." (PMID 33918875, 2021). "At 24 h after ischemic onset, increased CCL2 expression have also been observed in both the cerebrospinal fluid and serum of ischemic stroke patients." (PMID 35185544, 2021). "During the early phase of ischemic stroke, the prompt upregulation of CCL2 suggests its key role in recruiting innate immune cells, such as NK cells." (PMID 35185544, 2021). "Regulatory T cells ameliorate BBB damage after cerebral ischemia as well as hemorrhagic transformation after tPA administration following ischemic stroke in part by inhibiting CCL2 (monocyte chemoattractant protein 1) and MMP9." (PMID 30836997, 2019). "Another chemokine following ischemic stroke is CC (β) ligand 2 (CCL2) chemokine, also called a monocyte chemotactic protein-1 (MCP-1), produced by microglia cells, astrocytes, neurons, and inflowing leukocytes." (PMID 31514749, 2019). "Ischemic stroke induces the release of different chemokines such as CCL-2, CCL-3, CCL-4, CCL7, CCL-11, CXCL-1, CXCL10, from the ischemic tissue." (PMID 30584250, 2018). "Among the upregulated genes, Hspa1b, Ccl2, Cxcl2, Ccl3, Serpina3n, Timp1, H19, Hspb1, Ccl20, and Cxcl1 were found to demonstrate significant upregulation in pathological phase of ischemic stroke." (PMID 25861363, 2015). "Monocyte chemoattractant protein-1 (MCP-1, also known as CCL2) can recruit monocyte lineage cells following an inflammatory stimulus and contribute to ischemic stroke injury." (PMID 25418536, 2014).
ischemic stroke (continued). "Contrary to our findings, Hughes and colleagues (2006) reported that IL-6 and IL-1β were significantly reduced in the brains of Ccl2-/- mice after induction of ischaemic stroke." (PMID 20942978, 2010). "In this study, we demonstrated that among the inflammatory cytokines upregulated in the infarct region of the mouse photothrombotic ischemic stroke model, the induction levels of Cxcl10, Ccl2, and Tnfa mRNAs were substantially higher in the old mice than in the young ones." (PMID 40867143, 2025). "Therefore, future studies should focus on long-term consequences of modulated CCL2 expression in ischemic stroke." (PMID 39272984, 2024). "CCR2 is the main receptor that binds to CCL2 in ischemic stroke." (PMID 37452512, 2023). "The mechanism of the CCL2/CCR2 axis in ischemic stroke can be explained as follows." (PMID 37452512, 2023). "A study found that CCL2 is highly expressed in ischemic stroke tissues, which may promote the progression of ischemic stroke by activating chemokine signaling pathway and cytokine-cytokine receptor interaction pathway." (PMID 38154101, 2023). "Besides the most frequently discussed CCL2, other chemokines are also involved in the pathogenesis of ischemic stroke." (PMID 35794095, 2022). "For instance, C‐C motif chemokine ligand 2/monocyte‐chemoattractant protein‐1 (CCL2/MCP1) is known to substantially increase after diverse cerebrovascular diseases including ischemic stroke, and its levels even positively correlate with detrimental patients' outcome." (PMID 35971650, 2022). "Inflammatory M1 microglia secret inflammatory factors such as TNF-α, iNOS and CCL2 to promote inflammatory processes, which may aggravate autologous brain damage in the early stage of ischemic stroke." (PMID 33532127, 2021). "In other tissue contexts, recent reports indicate that progestin suppressed TNF-α induced proliferation and CCL2 secretion of endometrial stromal cells in vitro, while P4 prevented macrophage infiltration to brain endothelial cells by blocking CCL2 action after an ischemic stroke." (PMID 28966800, 2017). "Increased expression of CCL2 in MCAo model in the ipsilateral hemisphere was observed on neurons at 12 h and on astrocytes at 24 h after cardiac arrest, suggesting that these cells are the potential source of CCL2 during ischemic stroke." (PMID 24324296, 2013). "CCL2 activates the downstream target P2X4R, which has a dual effect on the progression of ischemic stroke." (PMID 37452512, 2023). "Our results have revealed that ischemic stroke results in upregulated expression of adhesion molecules (P‐selectin, E‐selectin, and ICAM‐1) and chemokines (CCL‐2, CCL‐3, CCL‐4, CCL‐5, and CXCL‐1)." (PMID 37122157, 2023). "In summary, ischemic stroke results in upregulated expression of adhesion molecules (P‐selectin, E‐selectin, and ICAM‐1) and chemokines (CCL‐2, CCL‐3, CCL‐4, CCL‐5, and CXCL‐1)." (PMID 37122157, 2023). "In the present study, we also found CCL2 and CCR2 levels to be significantly increased in the blood of our ischemic stroke patients." (PMID 33918875, 2021). "CCL2 (monocyte chemoattractant protein-1, MCP-1) and CCL9 (macrophage inflammatory peptide gamma, MIP-1γ) are chemokines upregulated after ischemic stroke in humans and rodents." (PMID 32872405, 2020). "An interaction effect of ischemic stroke and aging was observed for Cxcl10 and Ccl2, with p-values of 0.079 and 0.075, respectively, but not for Tnfa." (PMID 40867143, 2025). "ELISA showed that CCL2 was enriched in conditioned media from Slc4a4-depleted astrocytes under both normal (50% increase) and oxygen-glucose deprivation (OGD) conditions (70% increase), the latter mimicking in vivo ischemic stroke." (PMID 38709635, 2024). "In a model of ischemic stroke, CD36 KO mice had reduced CCL2/CCR2 expression." (PMID 37452512, 2023).
ischemic stroke (continued). "Remarkably, defective VDR signaling in microglia/macrophages resulted in pronounced upregulation of chemokines after acute ischemic stroke, including CXCL10 and CCL2, together with aggravated disruption of the BBB and infiltration of peripheral T cells and monocytes/macrophages." (PMID 36890539, 2023). "Therapeutic approaches regulating CCL2/CCR2 expression may alleviate the symptoms and pathologies of ischemic stroke." (PMID 35794095, 2022). "The MCAO challenge itself induced a significant up-regulation of pro- and anti-inflammatory genes in the brains of both control and treatment animals, including IL-6, IL-1β, TNF-α, IL-10, CCL2, and CCL3, indicating a pivotal role of neuroinflammation in the pathology of acute ischemic stroke events." (PMID 30126083, 2018). "Additionally, MCP-1 released by neutrophils and endothelial cells mobilizes circulating monocytes to infiltrate the site of ischemic stroke injury, and protease PR3 released by neutrophils upregulates the expression of endothelial ICAM-1 and CCL2 to enhance macrophage recruitment." (PMID 40746532, 2025). "After ischemic stroke, TREM2-KO mice exhibit reduced microglial activity, with decreased transcription of pro-inflammatory cytokines TNFα, IL-1α, and IL-1β, as well as reduced transcription of chemokines CCL2 (MCP1), CCL3 (MIP1α), and chemokine receptor CX3CR1." (PMID 39649720, 2024).
breast tumor (95 papers, 2004 to 2026). "CCL2 expression was negatively associated with the expression of both ER and PR in breast tumor tissues and more strongly associated with the expression of PR." (PMID 37208442, 2023). "CCL2 expression by breast tumors is associated with high tumor grade, angiogenesis, metastasis, and poor prognosis." (PMID 34771552, 2021). "Inflammation can also promote tumor growth, and increased CCL2 expression is correlated with more aggressive breast tumors as well as recruitment of tumor-associated macrophages." (PMID 32731354, 2020). "In breast tumors, CCL2 overexpression was associated with advanced disease, tumor progression, and angiogenesis, and predicts prognosis and recurrence." (PMID 32471499, 2020). "Previous studies demonstrated that CCL2 is synthsized by breast tumors and the stroma recruitment metastasis-associated macrophages, and this promoted metastasis in vivo and shortened the survival rate of tumor-bearing mice." (PMID 25695619, 2015). "Tumor-derived parathyroid hormone-related peptide (PTHrP) drives myeloid cell recruitment via osteoblast-produced chemokine (C-C motif) ligand 2 (CCL2), which is high in the bone microenvironment and whose levels are associated with poor prognoses in primary breast tumors." (PMID 31766386, 2019). "Furthermore, increased CCL2 protein expression in breast tumor tissues are associated with macrophage levels, and correlate with tumor grade and poor patient prognosis." (PMID 31208996, 2019). "Cancer development and progression could be decreased by 6-shogaol via inhibiting the production of inflammatory mediator chemokine (C-C motif) ligand 2 (CCL2), derived from breast tumor-associated dendritic cells (TADCs)." (PMID 27529277, 2016). "Recently, evidences showed that CCL2 was associated with breast tumor metastasis to brain." (PMID 25993304, 2015). "One report noted coordinated over-expression of TNF-α, IL-1β, and chemokines (CCL2, CCL5) in breast tumors, which was associated with epithelial–mesenchymal transition (EMT) and invasive behavior." (PMID 41007766, 2025). "Overall, breast tumor conditioned media inhibit myoblasts and myotubes, with some similar effects to those of high CCL2 treatment." (PMID 38973385, 2024). "TNFα is present in high concentrations in the breast tumor/stroma milieu and upregulates CCL2 production in 4T1 cells in vitro." (PMID 37208442, 2023). "The chemokine CCL2/MCP-1 (macrophage chemotactic protein-1) is highly expressed in breast tumors and stromal cells." (PMID 37373025, 2023). "PYK2 depletion significantly reduced the levels of secreted CCL2 from human and mouse BC cell lines in vitro, as well as the level of CCL2 in breast tumor lysates." (PMID 35092356, 2022). "This recognition was confirmed in a study conducted on mice, which proved that CCL2 acquires the ability to induce breast-tumor metastasis formation in lungs via VEGF." (PMID 35408440, 2022). "For instance, Qian et.al demonstrated that CCL2 recruited inflammatory monocytes to facilitate breast-tumor metastasis." (PMID 36230833, 2022). "We observed that the proportion of MDSCs in breast tumors was also reduced in situ, indicating that CCL2 promoted tumor growth in situ." (PMID 34249913, 2021). "Surprisingly, in CCL2−/− mice, neither PBS control nor exosome-trained group showed BC metastatic nidus, which strongly suggested that promotion of breast tumor-derived exosomes in lung metastasis was dependent on the expression of CCL2 in vivo." (PMID 34249913, 2021). "Macrophages have been shown to play a key role in the development of these tumors, in which CCL2 recruits inflammatory monocytes to facilitate breast tumor growth and metastasis." (PMID 34353349, 2021). "CCL2 has an established role in recruiting inflammatory macrophages into breast tumors to increase primary tumor growth and metastasis." (PMID 34045467, 2021).